MRE11 (MRE11 double strand break repair nuclease)
Diseases named in the same sentence as MRE11 in open-access papers (continued):
Sharing a sentence is not in itself a finding about the gene and the disease.
tumor (121 papers, 2008 to 2025). "In summary, inhibition of Mre11 nuclease activity through gene mutation precludes or attenuates tumor promotion." (PMID 37754262, 2023). "Our IHC clinical data provide evidence that MRE11 overexpression in BRCA2-deficient somatic tumours can influence aggressive clinicopathological phenotypes." (PMID 37446144, 2023). "In Kaplan–Meier survival analyses, we found that high MRE11 expression in the tumor center (TC) was significantly associated with poor disease-free survival (DFS; p = 0.045) and overall survival (OS; p = 0.039)." (PMID 37173905, 2023). "While upregulation of MRN complex has been associated with a high tumor grade, chemo/radiotherapy resistance, and poor overall and progression-free survival, deficiency in MRE11 predicts a better prognosis." (PMID 34201502, 2021). "MSI status was used as a surrogate marker of MRE11 deficiency, due to a previously identified association between MSI tumours and MRE11 mutations." (PMID 34440228, 2021). "Immunohistochemistry analysis of BC and OC tumours from carriers showed strong protein expression of MRE11, and genetic analyses of tumour tissues revealed the presence of both parent of origin MRE11 alleles." (PMID 34298626, 2021). "MRE11 depletion represses tumor growth enhanced by HP1α deficiency, suggesting a connection between CLIC and tumorigenesis." (PMID 34363353, 2021). "Herein, we modeled twenty-five RAD50 and MRE11 tumor alleles in yeast and in vitro in an attempt to shed light on the tumor suppressive function(s) of the complex." (PMID 32187176, 2020). "Yeast RAD50 and MRE11 mutants corresponding to tumor borne alleles were integrated into a diploid yeast strain at their respective chromosomal loci, and haploid spores were derived by tetrad dissection." (PMID 32187176, 2020). "The identification of Mre11 complex tumor-borne alleles and modeling of their consequences in mice and yeast has been invaluable for understanding the Mre11 complex’s roles in the DDR." (PMID 32187176, 2020). "In fact, immunohistochemistry and immunofluorescent assays demonstrated that tumor cells carrying S633T or S638P mutations were observed to be deficient in the nuclear localization of MRE11." (PMID 32668560, 2020). "The histone deacetylase (HDAC) inhibitor Panobinostat can downregulate MRE11 and other proteins associated with homologous recombination and radiosensitize tumor cells." (PMID 31767017, 2019). "We have previously shown that high tumour protein levels of MRE11, as determined by immunohistochemistry, were associated with improved patient outcome following radio therapy in MIBC patients." (PMID 31942442, 2019). "Associations between the combined expression of ATM and MRE11 in the tumor center and tumor periphery and clinicohistopathological data." (PMID 27930716, 2016). "Loss of MRE11 protein was found in 30.7% of EC tumours and significantly associated with loss of RAD50, NBS1 and mismatch repair protein expression." (PMID 24927325, 2014). "After statistical analysis, we found strong expression of MRE11 (P = 0.016) to be significantly associated with low tumor grade." (PMID 24752797, 2014). "A feature displayed by the Mre11ATLD/ATLD mutation might explain the different tumor-promoting activities of MRN component Mre11 versus Nbs1 and ATM." (PMID 37754262, 2023). "With respect to MB, not only has it been sporadically described in NBS patients, but heterozygous germline or somatic NBN, RAD50 and MRE11 mutations were discovered in MB patients, implying their potential role as haploinsufficient tumour suppressors for MB development." (PMID 35839783, 2022).
tumor (continued). "Using RT Profiler PCR Array—Human Tumor Metastasis (SABioscience), which evaluates 84 genes involved in different tumor metastasis pathways, we compared differential RNA expression of tumor metastasis-associated genes when MRE11 was overexpressed." (PMID 33927349, 2021). "In summary, our study reveals that tumor borne alleles (rad50-D67N/Y, rad50-R1259C, mre11-E38K, and rad50-L1240F) found in 25 distinct tumors exhibit separation of function phenotypes specifically impairing Tel1 activation, while only partially affecting DSB repair." (PMID 32187176, 2020). "Interestingly, in the tumor containing the T90S variant, immunohistochemistry showed down regulation of nuclear localization of MRE11." (PMID 32668560, 2020). "We hypothesized that acquired deficiencies in ATM and/or MRE11 would lead to a dysfunctional repair mechanism and an inability to restore genomic stability, resulting in increased tumor cell death following radiotherapy." (PMID 27930716, 2016). "First, MRE11-deficiency might be a useful marker for tumor prognosis; and second, that MRE11-deficient (dMRE11) tumors might respond better to treatment with topoisomerase 1 poisons than MRE11-proficient (pMRE11) tumors." (PMID 25310185, 2014). "It has been reported that inhibition of PI3K/Akt signaling pathway led to radiosensitize the tumor cell by affecting repair of DNA double-strand breaks via DNA-PKcs, and this pathway inactivates Bad and caspase-9 and activates p21, p27 and Mre11, which are associated with cellular radiosensitivity." (PMID 23777562, 2013). "Our group recently reported that elevated MRE11 expression is associated with increased OSCC tumor growth and metastasis; in addition, a higher expression level of MRE11 in patients is predictive of poorer survival under radiation therapy compared to those with a lower expression level of MRE11." (PMID 35629265, 2022). "MRE11-deficiency may affect both clonal evolution within a tumor as well as therapeutic response." (PMID 25310185, 2014). "For instance, MRE11-K673la promoted DNA binding and enhanced homologous recombination repair, leading to tumor cell resistance to cisplatin and PARP inhibitors." (PMID 40484921, 2025). "In vivo tumor volume and weight analyses validated these findings, demonstrating that lactylation of MRE11 at Lys673 is a central mediator of radioresistance." (PMID 40963916, 2025). "Immunohistochemistry for histone H3S10ph also revealed a high mitotic index in Mre11 mutant tumours." (PMID 38200309, 2024). "After tumour onset, Mre11 mutant tumours exhibited rapid growth, which resulted in a shorter time interval from initial palpation to tumour collection." (PMID 38200309, 2024). "Our data show that this fork slowdown is suppressed by Mirin, suggesting that the tumor-suppressive function of MRE11 comes at the cost of slower replication." (PMID 38926338, 2024). "Our study also highlighted the significance of ZBP1-dependent necroptosis as an effector of MRE11–cGAS-mediated tumour suppression." (PMID 38200309, 2024). "While MRE11 has been described as disrupted in over 60% of dMMR/MSI CRC, it has been suggested that MRE11 expression is strongly correlated with the activation of the immune response, as evidenced by higher levels of tumor-infiltrating inflammatory cells." (PMID 37372450, 2023). "Pretreatment tumor tissues were processed for immunofluorescence with anti-MRE11 antibody and analyzed using automated quantitative image analysis to calculate a normalized score for MRE11 based on nuclear-to-cytoplasmic (NC) signal ratio." (PMID 36383379, 2022).
tumor (continued). "Of 465 patients with nonmetastatic MIBC enrolled in 6 prospective RTOG clinical trials of trimodality therapy, 168 patients had tumor tissues analyzable for MRE11 expression, of which 135 (80.4%) were analyzable for MRE11 NC ratio." (PMID 36383379, 2022). "Of the primary tumours, 325 were low Mre11, and 90 were high MRE11 (significantly lower in Q1 vs Q4 log2FC = −1.283840657)." (PMID 35853939, 2022). "Low MRE11 expression reduces phosphorylated DNA-PKcs expression, further increases tumor radiosensitivity." (PMID 35875060, 2022). "In the TCGA cohort, we observed a subset of tumours with Mre11 amplification which was strongly correlated with high Mre11 mRNA expression." (PMID 35853939, 2022). "The glp-1(ar202gf) lifespan is extended by the RNAi-mediated knockdown of mre-11 plus gamma irradiation because inhibiting homologous recombination increases radiation sensitivity and tumor reduction in the distal region of the worm germline." (PMID 36230851, 2022). "Low MRE11 expression in colorectal cancer cells reduced phosphorylated DNA-PKcs expression and further increases tumor radiosensitivity." (PMID 35875060, 2022). "MRE11 is the core protein of the RAD50/MRE11/NBS1 complex with a primary role in DNA damage repair, and it has been diversely associated with tumor development including OSCC." (PMID 35629265, 2022). "As expected, patients whose tumours had low XRCC1/low Mre11 co-expression (22.8%) had better progression free survival (p = 0.014) and overall survival (p = 0.005) compared to tumours that had high XRCC1/high Mre11 co-expression (48.7%)." (PMID 35853939, 2022). "Conversely, the subtype-2 tumours expressed significantly higher levels of several proteins, including Stathmin, Mre11 and MAP2K1, than the subtype-1 tumours." (PMID 34506537, 2021). "Although rare, we observed a complete loss of MRE11 expression in 14% (90/659) of tumours, complete loss of RAD50 expression in 5% (40/733) of tumours and complete loss of NBS1 expression in 9% (109/1166) of tumours." (PMID 34782604, 2021). "Smaller tumor volume was observed in MRE11 knockdown group (shMRE11) compared to control group (shLuc)." (PMID 33927349, 2021). "The data reveal that the signaling functions of the Mre11 complex are important for tumor suppression to a greater degree than its role in DNA repair." (PMID 32187176, 2020). "We found that a significant fraction of tumor-borne RAD50 and MRE11 mutations exhibited separation of function phenotypes wherein Tel1/ATM activation was severely impaired while DNA repair functions were mildly or not affected." (PMID 32187176, 2020). "This study aimed to investigate the expression of MRE11 in tumor tissue and defining its value in predicting prognosis of PCa patients." (PMID 31413753, 2019). "MRE11 overexpression in GC tissues was significantly related to lymph node metastasis (P < 0.05), distant metastasis (P < 0.05) and tumour-node-metastasis (TNM) stage (P < 0.05)." (PMID 31221177, 2019). "In a multivariate analysis, MRE11 expression remained a strong prognostic value, after adjusting for tumor stage, the grade of differentiation and TIICs (HR = 0.37, 95% CI = 0.18–0.76, P = 0.007)." (PMID 32010608, 2019). "MRE11 protein expression was evaluated in normal mucosa, primary tumor and lymph node metastasis (LNM) sections by immunohistochemistry." (PMID 32010608, 2019). "Some studies have suggested that high expression of MRE11 in tumour cells enhances DSB repair, leading to increased local recurrence and reduced survival rates." (PMID 31221177, 2019). "It remains uncertain which function of MRE11 or the MRN complex plays a dominant role in tumor progression." (PMID 31767017, 2019).
tumor (continued). "MRE11 protein expression in tumour tissues from 155 GC patients was analysed by immunohistochemistry." (PMID 31221177, 2019). "Given previous reports from the same group linking tumor MRE11 expression levels with radiation outcomes, this germline association is compelling, but requires validation in an independent radiation-treated cohort." (PMID 28346378, 2017). "We observed decreased expression levels of genes associated with DNA repair (MRE11, RAD51) and genes involved in cell cycle and chromosomal segregation (PLK1) after FOXM1 inhibition in both GBM tumor cells and stem cells." (PMID 27764801, 2016). "We have investigated a number of post-transcriptional mechanisms, and found that miRNA-153 expression was inversely correlated with MRE11 expression, although miR-153 was only highly expressed in a few tumours, limiting its clinical applicability." (PMID 24625413, 2014). "The aim of this study was to further investigate our observation that patients with low tumour MRE11 expression do worse following radical radiotherapy than high MRE11 expressors." (PMID 24625413, 2014). "Our finding that low tumour MRE11 expression is predictive of poor response to radiotherapy but not cystectomy was recently independently validated." (PMID 24625413, 2014). "MMR-deficient CRC tumours and cell lines frequently tend to accumulate mutations within microsatellite repeats of genes implicated in DSB repair pathway (eg, MRE11 and RAD50), suggesting an enhanced sensitivity of these tumours to camptothecin analogues." (PMID 18941461, 2008). "Consequently, tumor cells with hyperlactylated MRE11/NBS1 display marked chemoresistance, and pharmacologic blockade of lactate production (via LDHA inhibition) restores therapeutic sensitivity." (PMID 41583433, 2025). "Tumours with low PRDX1/MRE11 co-expression have favorable PFS as well as overall survival (OS) compared to tumours with high PRDX1/MRE11." (PMID 40387816, 2025). "Administration of CBP or LDH inhibitors, or cell-penetrating peptides that can specifically block the lactylation of MRE11, can reduce the lactylation of MRE11, inhibit HR, and enhance the sensitivity of tumor cells to chemotherapeutic agents such as cisplatin, PARPi, etc." (PMID 40399304, 2025). "In this regard, MRE11 may play stage-dependent roles, by limiting tumor initiation through cGAS activation and immunosurveillance and promoting tumor progression and chemoresistance by enhancing DNA damage repair." (PMID 39872378, 2024). "MRE11, a nuclease pivotal in initiating DNA end cleavage and homologous recombination repair, is thereby regulated by the lactic acid-mediated modification, contributing to the homologous recombination repair process in tumor cells." (PMID 38672455, 2024). "Additionally, Mre11 mutant tumours displayed an increased frequency of mitotic aberrations, particularly chromatin bridges." (PMID 38200309, 2024). "Recent studies indicate that tumor cells metabolize lactic acid, and this metabolic process can facilitate lactate modification, subsequently modulating the activity of meiotic recombination 11 homolog 1 (MRE11)." (PMID 38672455, 2024). "Targeting Mre11 significantly shortened tumour latency compared with the control sgRNA." (PMID 38200309, 2024). "Notably, we report that for one of them, MRE11, its relatively high expression was associated with the pejorative features of CRC, i.e., right-sided colon tumors, increased tumor invasive depth, higher tumor grade, MMR deficiency, and poorer overall survival." (PMID 37372450, 2023). "As the PEO1R xenografts were highly tumorigenic, we speculated that MRE11 could also have predictive and/or prognostic significance in human tumours." (PMID 37446144, 2023). "As the core component of MRN complex, MRE11 plays a vital role in the process of DNA double-strand break repair, and the functional variation of MRE11 can significantly influence the efficacy of tumor therapies targeting DNA damage." (PMID 37759323, 2023).
tumor (continued). "Tumours were separated into quartiles depending on the level of Mre11 mRNA." (PMID 35853939, 2022). "We identified copy number gains in Mre11 and in 5% cases (10/201 tumours) amplification." (PMID 35853939, 2022). "When nuclear and cytoplasmic expression of Mre11 was combined together, we observed that high nuclear/high cytoplasmic levels of Mre11 was associated with poor PFS (p = 0.016) and poor OS (p = 0.007) compared to tumours with low nuclear/low cytoplasmic Mre11 expression." (PMID 35853939, 2022). "These loss-of-function RAD50 mutations could restrict MRE11-mediated degradation of nascent DNA at challenged replication forks in PARP-resistant, BRCA1/2-PALB2-mutated cells, and may help to explain tumor chemoresistance." (PMID 35501303, 2022). "Transcriptome analysis suggests the enhanced DSB repair in tumor cells in the OB can be attributed to an increased expression of a group of genes (MRE11, XRCC5, XRCC6 and PRKDC) essential to the NHEJ pathway of DSB repair, which is a critical determinant of radiosensitivity." (PMID 36482431, 2022). "The present data aid in our understanding of this control process and further suggest that potential therapeutic approaches to trigger fusion in tumor cells with TRF2-containing dysfunctional telomeres (such as ALT-dependent tumors) will need to account for both MRE11 and UBR5 to be successful." (PMID 34881184, 2021). "In the ER+ cohort, similarly, low nuclear MRE11 was strongly linked with poor BCSS (p = 0.00006) but not in ER− tumours (p = 0.121)." (PMID 34782604, 2021). "In the present study, we analyzed the MRE11 expression and prognosis in different tumor location." (PMID 32010608, 2019). "To investigate the MRE11 expression in tumor tissue and defining its value in PCa patients, we enrolled 78 patients who have received previous radical prostatectomy in our institution and validate its role in 500 patients in the Cancer Genome Atlas (TCGA) database." (PMID 31413753, 2019). "Whether MRE11 expression in different tumor location of CRC has a significant prognostic impact is yet to be manifested." (PMID 32010608, 2019). "While these data match the renowned tumor suppressive function of MRE11, they also highlight that its inhibition might be detrimental in non-MYCN-driven tumors." (PMID 30166519, 2018). "ATM and MRE11 protein expression levels in the TC were tested in a forward and reverse binary logistic regression analysis using a data set of immunohistochemical scoring derived from 257 tumor samples and 255 normal tissues." (PMID 27930716, 2016). "The treatment with Mre11 siRNA increases human tumor cells radiosensitivity." (PMID 26951044, 2016). "The MRE11/ATM two-protein panel developed in this study may have clinical value as a predictive marker of tumor response to neoadjuvant radiotherapy, and a prognostic marker for disease-free and overall survival." (PMID 27930716, 2016). "Similarly, ATM and MRE11 protein expression levels in the TP (tumor, n = 258; normal, n = 255) were also tested, and the model gave an average ROC-AUC value of 0.837." (PMID 27930716, 2016). "Although speculative, this list could include other key HDR genes including ATM, BRCA1/2, MRE11, RAD50, NBS1 or RAD51, which are also mutated in CRC and many other tumor types." (PMID 26318585, 2015). "It is therefore likely, at least in mice, that ROS signaling via ATM is largely intact and this could be sufficient for tumor suppression in Mre11 complex mutants." (PMID 23532176, 2013). "The deletion of the checkpoint kinase Chk2 in any murine backgrounds with defects in the G2/M checkpoint, including Chk1 heterozygotes, and particular Mre11 complex or BRCA1 alleles, results in tumor predisposition, indicating that the G2/M transition is important for tumor suppression." (PMID 23532176, 2013).